STAT5B (signal transducer and activator of transcription 5B)
Diseases named in the same sentence as STAT5B in open-access papers (continued):
Sharing a sentence is not in itself a finding about the gene and the disease.
hematologic malignancies (11 papers, 2013 to 2025). "Being the most common and specific for this disorder, STAT3 mutation currently remains the genetic marker suggestive of LGLL, whereas STAT5b gene is frequently described mutated also in many other hematologic diseases beyond LGLL." (PMID 32133291, 2020). "In the HSTL sample in our analysis, we identified a somatic mutation in a highly conserved residue in the SH2 domain of STAT5B encoding a N642H mutation, a prolific oncogenic mutation found in many hematologic malignancies." (PMID 26536348, 2015). "In that sense, the activation of STAT5B might be an asset during transformation and explain why gain-of-function mutations are found in hematological disorders at increased frequency." (PMID 30679796, 2019). "Demonstration of a critical role of Stat5b in hematologic malignancies has generated increasing interest in the mechanisms through which Stat5b functions as an oncogene." (PMID 23457589, 2013). "The apparent discrepancy between STAT5B’s predominantly protective associations in our analysis and prior reports of oncogenic STAT5B mutations (e.g., STAT5BN642H) in hematologic malignancies can be reconciled by considering activation state and mutational context." (PMID 41301421, 2025). "Finally, a preeminent role for STAT5B over STAT5A has been broadly observed across several hematological malignancies." (PMID 38254802, 2024). "We also examined the frequency of STAT3 and STAT5B mutation in hematologic diseases without T-LGL." (PMID 37142644, 2023). "As a member of the STAT family, STAT5B plays a key regulatory role in the pathogenesis of various disease drivers, including BCR/ABL and NPM-ALK, and expresses at a high level in hematological malignancies." (PMID 34895266, 2021).
hematopoietic cancers (7 papers, 2019 to 2025). "Many CIS occurred near genes implicated in hematologic cancers and hematopoietic development (Erg, Ets1, Epo, Il2rb, Flt3, Kras, Stat5b, Fli1)." (PMID 30940846, 2019). "Overexpression of STAT5B is strongly correlated with the proliferation of multiple hematopoietic cancers and several oncogenic activating mutations have been identified." (PMID 31175292, 2019). "Importantly, most somatic GOF mutations of STAT3 and STAT5B occur in hematopoietic cancers within the SH2 domain, further emphasizing its importance for STAT function, particularly in blood cells." (PMID 30818760, 2019). "Our findings might help explain the high frequency of STAT5B mutations in hematopoietic tumors." (PMID 30679796, 2019). "STAT3 and the two closely related STAT5A and STAT5B proteins are key players in the development of solid and haematopoietic cancers." (PMID 32667731, 2020). "Our data may be of direct clinical relevance: current studies propose STAT5B as a key driver in human hematological tumors." (PMID 30679796, 2019). "As mutations in STAT5B, but not STAT5A, have been frequently described in hematopoietic tumors, we used BCR/ABL as model systems to investigate the contribution of STAT5A or STAT5B for leukemogenesis." (PMID 30679796, 2019).
blood cancer (2 papers, 2022 to 2025). "Tyrosine 665 is the second most abundant mutational target in the STAT5B SH2 domain, with 53 blood cancer cases identified in the Munich Leukemia Laboratory database and 12 blood cancer cases reported in the COSMIC database." (PMID 40228864, 2025).
Cardiovascular Disease (1 paper, 2015). "HMOX1, PDGFB, Ins, VEGF, and STAT5B are key nodes in the “Cardiovascular Disease, Lipid Metabolism, Molecular Transport” network and also interact with other DE genes." (PMID 25774290, 2015).
endocrinopathies (1 paper, 2025). "Other genetic defects that lead to endocrinopathies include loss-of-function changes in IL2RA, STAT5B and GOF in STAT3 and STAT1." (PMID 40704637, 2025).
gastrointestinal tumor (1 paper, 2024). "We further found NOTCH3 levels in gastrointestinal tumor to correlate with markers of Dendritic cell(HLA-DPB1, HLA-DRA, HLA-DPA1, BDCA-4), Tfh(T-bet, STAT4, STAT1, TNF-α), Treg cells (FOXP3, CCR8, STAT5B, TGFβ) and T cell exhaustion (PD-1, CTLA4, LAG3, TIM-3)." (PMID 38906903, 2024).
infectious disease (1 paper, 2022). A disorder directly resulting from the presence and activity of a microbial, viral, or parasitic agent in humans. "And sixteen genes of ‘Antimicrobial Response, Infectious Diseases and Inflammatory Response’ as the top network of RSK2 KO-specific DEGs were shown to have three DEGs highly correlated with RSK2 expression with significant R and p values (ISG15, LYN and STAT5B)." (PMID 36684450, 2022).
kidney disease (1 paper, 2016). "Not surprisingly, there was a marked accumulation of CD44high IL-7Rαlow effector/memory T cells in Stat5b-deficient mice which, as with the incidence of kidney disease, was more pronounced in those bearing one-allele of Stat5a than in those bearing two." (PMID 26999798, 2016). "Our work clearly endorses this viewpoint and brings to mind the autoimmune phenotype of Treg-deficient Scurfy mice which, like Stat5b-deficient mice, exhibit both autoantibodies and kidney disease {Aschermann:2013gn}." (PMID 26999798, 2016). "This principle is well illustrated in humans with congenital STAT5B defects, who typically manifest a range of autoimmune symptoms, and is further supported by the present work, which demonstrates that Stat5b deficiency leads to spontaneous kidney disease in mice." (PMID 26999798, 2016).
STAT5B also shares sentences with these, for which no sentence is quoted: chronic myelogenous leukemia, BCR-ABL1 positive (3 papers); endometrial cancer (3); autoimmune thyroiditis (2); B-cell acute lymphoblastic leukemia (2); chronic lymphocytic leukemia (2); Glucose intolerance (2); hypothyroidism (2); inflammatory bowel disease (2); Insulin resistance (2); invasive ductal breast carcinoma (2); juvenile idiopathic arthritis (2); kidney injury (2); leukoplakia (2); metabolic disease (2); pulmonary disease (2); pulmonary fibrosis (2); Wiskott-Aldrich syndrome (2); acute kidney injury (1); adenocarcinoma (1); adrenocortical tumors (1); adult T-cell leukemia/lymphoma (1); Allergy (1); alpha-synucleinopathy (1); Alzheimer disease (1); anaplastic astrocytoma (1); aplastic anaemia (1); Arthritis (1); astrocytoma (1); autism spectrum disorder (1); bacterial infections (1).
A further 65 diseases each share a sentence with STAT5B in 1 paper.